AFP (alpha fetoprotein)
Diseases named in the same sentence as AFP in open-access papers (continued):
Sharing a sentence is not in itself a finding about the gene and the disease.
hepatocellular carcinoma (continued). "We also found that patients with larger tumors, hepatic cirrhosis, portal vein thrombosis, metastasis, and massive hepatocellular carcinomas had higher serum AFP levels." (PMID 35461226, 2022). "Among them, alpha-fetoprotein (AFP), a known marker for liver injury and hepatocellular carcinoma secreted by hepatic progenitor cells was significantly more abundant in the lysates of reprogrammed VLK KO cells." (PMID 35293576, 2022). "AFP has been widely accepted as a tumor marker for hepatocellular carcinoma in population-based screening and surveillance for many years." (PMID 36556261, 2022). "This study was conducted to investigate the effect of alpha-fetoprotein (AFP) ratio on the prognosis of AFP-positive hepatocellular carcinoma (HCC) patients after hepatectomy." (PMID 35059044, 2022). "Approximately 20% of ICC patients are AFP-positive, and these patients are often misdiagnosed as hepatocellular carcinoma (HCC) before pathological diagnosis." (PMID 36556261, 2022). "Alpha-fetoprotein (AFP) is the most widely used biomarker for hepatocellular carcinoma (HCC) prognosis." (PMID 35053564, 2022). "Alpha-fetoprotein (AFP) is a tumor marker secreted by different levels of hepatocellular carcinoma and therefore is often used as one of the few means to detect hepatocellular carcinoma." (PMID 36479313, 2022). "AFP is the most commonly used biomarker for hepatocellular carcinoma, but the level of AFP is also increased in other benign liver diseases." (PMID 36293285, 2022). "Alpha-fetoprotein has been the most widely used biomarker for hepatocellular carcinoma during the past several decades and is considered the gold standard by which other markers for the disease are judged." (PMID 35845304, 2022). "Then, we assessed the bioactivity of the fragment in the human liver cancer cell line Bel7402, and the results indicated that the AFP fragment synergized with sorafenib to inhibit the hepatoma cell growth and migration and promote the apoptosis." (PMID 36181321, 2022). "At present, glycosylated proteins have become one of the most common tumor biomarkers in clinic, such as alpha fetoprotein (AFP) of hepatocellular carcinoma, carcinoembryonic antigen (CEA) of colon cancer and prostate specific antigen of prostate cancer." (PMID 35680565, 2022). "The prevention and treatment of hepatocellular carcinoma in HepG2 cells were initiated by EGCG by regulating α-fetal protein (AFP) secretion, thereby modulating autophagy." (PMID 34201882, 2021). "AUC and the corresponding 95% CI of serum microRNA and AFP in patients with hepatocellular carcinoma compared with healthy controls." (PMID 34163524, 2021). "The aim of this review is to summarize the current knowledge of the role of alpha-fetoprotein in hepatocellular carcinoma." (PMID 34680245, 2021). "The HCC biomarker AFP is also a regulator of growth signaling via PI3K/AKT signaling in hepatoma cells." (PMID 33801181, 2021). "Here, we show that HBP1 regulates AFP expression at the transcriptional level and inhibits the development of hepatoma." (PMID 33794968, 2021). "HBP1 low expression and/or AFP high expression in hepatoma can be correlated with low survival rate." (PMID 33794968, 2021). "The data suggest that the inverse expressions of HBP1 and AFP correlate with relapse and survival in hepatoma patients." (PMID 33794968, 2021). "Previous research revealed that high serum levels of AFP and ALT were associated with disease progression and poor prognosis in patients with hepatocellular carcinoma." (PMID 34615436, 2021). "Golgi protein 73 (GP73) and alpha fetoprotein (AFP) serve as biomarkers for the diagnosis of hepatocellular carcinoma (HCC), and their serum levels correlate with patients’ outcomes." (PMID 34650031, 2021). "The combination of annexin A2 and alpha-fetoprotein (AFP) improved the sensitivity in detecting early stage hepatocellular carcinoma." (PMID 33406648, 2021).
hepatocellular carcinoma (continued). "As everyone knew, serum alpha fetoprotein (AFP), as a carcinoembryonic glycoprotein, was the first to be studied as a biomarker of hepatocellular carcinoma by Abelev in 1968." (PMID 34961841, 2021). "In recent years, several serum biomarkers were used to detect the progression and prognosis of hepatocellular carcinoma, such as Alpha-fetoprotein (AFP) and Carcinoembryonic Antigen (CEA)." (PMID 34123827, 2021). "Cytoplasmic AFP can also function as a regulator of phosphatidyl-inositol-3-kinase (PI3K)/Akt signaling in human hepatoma cell lines." (PMID 33562077, 2021). "In this investigation, MPDA@SPIO/SA-PEI/AFP-Fth nanocomplexes as a novel diagnosis agent for targeting hepatoma cells was synthesized." (PMID 33731140, 2021). "Since HBP1 and AFP play a key role in the development of hepatoma, studies on the regulation of HBP1 and AFP are crucial in maintaining the normal physiological function of the liver and the diagnosis and treatment of liver cirrhosis and hepatoma." (PMID 33794968, 2021). "The relative expressions of HBP1 and AFP correlated with survival and prognosis in hepatoma patients." (PMID 33794968, 2021). "The common tumor markers in clinical use are dominant for various tumors, such as carcinoembryonic antigen (CEA) for colorectal cancer, alpha-fetoprotein (AFP) for hepatocellular carcinoma, Ca 12-5 for ovarian cancer, and so forth." (PMID 34335759, 2021). "HBx is a HBV regulatory protein that up-regulates AFP expression and promotes the development of HBV-associated hepatoma." (PMID 33794968, 2021). "The sensitivity and specificity of AFP to hepatocellular carcinoma (HCC) in all stages are 41–65% and 80–94%, respectively." (PMID 34348726, 2021). "AFP is the most commonly used detection index in the clinical diagnosis of early hepatocellular carcinoma." (PMID 34961841, 2021). "The serum content of AFP can be related to liver carcinomas, and APF is considered as an important diagnostic biomarker of hepatocellular carcinoma (HCC)–one of the most malignant tumours, representing 4.7% of all cancers." (PMID 33499136, 2021). "High doses (more than 100 mg/L) of purified human AFP were shown to strongly inhibit the growth of human hepatoma HepG2 cells, human lymphoblastoma MT4 cells, lymphoma Jurkat cells and murine fibroblastoma L929 cells in a dose-dependent manner." (PMID 34680245, 2021). "PARPBP, a significant inhibitor of homologous recombination (HR), has been demonstrated to be related to increased AFP levels, proliferation, differentiation, and poor prognosis of lung and hepatocellular carcinoma patients." (PMID 34568334, 2021). "Alpha fetoprotein (AFP) plays a key role in stimulating the growth, metastasis and drug resistance of hepatocellular carcinoma (HCC)." (PMID 33898423, 2021). "Alpha-fetoprotein is used as a tumor marker to follow the patients for hepatocellular carcinoma in conjunction with serial liver ultrasound." (PMID 34899923, 2021). "Icaritin, an active ingredient of Chinese herb epimedium, inhibited malignancy in hepatoma cells through enhancing HBP1 transrepression of AFP." (PMID 33794968, 2021). "Semenkova and coworkers proposed that a high dose of exogenous addition of AFP derived from different sources (cord serum and culture medium of AFP-secreting HepG2 cells) can induce dose-dependent apoptosis of human hepatoma HepG2 cells." (PMID 34680245, 2021). "The deregulation of AFP by HBP1 is associated with hepatoma cell metastasis and poor survival of hepatoma patients." (PMID 33794968, 2021). "Under different critical values, the sensitivity of AFP detection is 40%~65%, and the specificity is 76%~96%, with some false negative and false positive, which greatly limits the clinical application prospect of AFP monitoring hepatocellular carcinoma." (PMID 34961841, 2021). "Intracellular AFP promoted cellular proliferation and inhibited cellular apoptosis in hepatocellular carcinoma (HCC)." (PMID 33765973, 2021).
hepatocellular carcinoma (continued). "The study showed that the AFP plasmid containing an hCMV enhancer (hCMV/AFP) boosted the expression activity by ∼15- to 20-fold in hepatoma cell lines." (PMID 34348480, 2021). "Taken together, this shows the functionality in the hCMV/AFP element in promoting specificity and sensitivity for hepatocellular carcinoma both in vitro and in vivo." (PMID 34348480, 2021). "We observed a significant inverse correlation between HBP1 and AFP protein levels in hepatoma tissues by immunohistochemical staining." (PMID 33794968, 2021). "Alpha-fetoprotein (AFP) has been mostly used as a tumor marker for hepatocellular carcinoma, though it has also been suggested as a marker for CRC." (PMID 33977101, 2021). "ZHX2 was initially found as a negative regulation gene of AFP and was subsequently demonstrated to have a tumor suppressive role in hepatocellular cancer." (PMID 33837660, 2021). "The expression level of AFP in healthy adults is significantly lower than in the fetal period; however, AFP is detected in patients with hepatocellular carcinoma and some other cancers." (PMID 34648110, 2021). "AFP constitutes most of the serum proteins in the fetus and is considered a marker of hepatocellular carcinoma (HCC) and other tumors." (PMID 33289529, 2021). "The change in AFP was recently integrated into the validated Hepatocellular Carcinoma Early Detection Screening (including patient's current level of AFP, rate of AFP change, age, level of alanine aminotransferase, and platelet count) algorithm." (PMID 34754704, 2021). "As everyone knew, AFP, as a carcinoembryonic glycoprotein, was first to be studied as a biomarker of hepatocellular carcinoma by Abelev in 1968." (PMID 34961841, 2021). "The literature reveals that AFP, besides being one of the most useful biomarkers for the detection of hepatocellular carcinoma, also serves to monitor the response to anticancer therapy (high levels indicate tumor progression)." (PMID 34305611, 2021). "Alpha-fetoprotein in serum and cytoplasm shows very different influences in the tumorigenesis and progression of hepatocellular carcinoma." (PMID 34680245, 2021). "We recently demonstrated that icaritin inhibited the expression of cytoplasmic AFP in hepatitis B virus-infected hepatoma cells." (PMID 33765973, 2021). "The expression of transcription factor HBP1 and AFP and clinical significance were further analyzed in hepatoma tissues from the patients who received surgery or TACE and then monitored for relapse for up 10 years." (PMID 33794968, 2021). "It demonstrated a dual targeting strategy that combined active targeting of SA with the plasmid that consisted AFP promoter, which was propitious accumulated and expressed the report gene in hepatoma cells." (PMID 33731140, 2021). "Hepatocellular carcinoma developed in 4 (5.7%) patients, all with high alpha-fetoprotein values (p = 0.0043) and hypoechoic liver mass (p = 0.0001), three of these patients had diabetes mellitus type 2." (PMID 33652777, 2021). "AFP can also promote hepatoma cell migration and invasion by increasing the expression of cell migration-related genes such as K19, EpCAM, MMP2/9 and CXCR4." (PMID 33794968, 2021). "Li MS, Li PF, He SP, Du GG, Li G. The promoting molecular mechanism of alpha-fetoprotein on the growth of human hepatoma Bel7402 cell line." (PMID 34550233, 2021). "Second, in our study, AFP performed surprisingly well in detection of hepatocellular carcinoma, with AFP20 demonstrating very high specificity." (PMID 34206321, 2021). "Alpha-fetoprotein (AFP), a biomarker associated with hepatocellular carcinoma, was used as a model protein for evaluating the method." (PMID 32752243, 2020). "Combined with ultrasound measurement in detecting early stage hepatocellular carcinoma, AFP is still inefficient with extremely low sensitivity (63%), which leads to a high misdiagnosis rate." (PMID 32783378, 2020).
hepatocellular carcinoma (continued). "Serum alpha-fetoprotein (AFP) is the approved serum marker for hepatocellular carcinoma (HCC) screening." (PMID 33371894, 2020). "The role of α-fetoprotein (AFP) in the surveillance and diagnosis of hepatocellular carcinoma (HCC) has been questioned in recent years due to its low sensitivity and specificity." (PMID 33015170, 2020). "Then the expression of AFP and its genomic background in hepatocellular carcinoma (liver cancer) was studied." (PMID 31897235, 2020). "The expression of PAQR3 is decreased and closely associated with serum alpha-fetoprotein (AFP), clinical stage, tumor size, and survival time in hepatocellular carcinoma." (PMID 33123538, 2020). "Liver function and CEA were normal in the HEHE group, although AFP was elevated in one case of HEHE with hepatocellular carcinoma." (PMID 32600273, 2020). "The first CAR T cells expressing a TCRm scFv for alpha fetoprotein (AFP)-HLA-A*02 recently advanced to human trials for the treatment of hepatocellular carcinoma." (PMID 33569049, 2020). "In conclusion, T3/TR regulates expression of TUG1 and AFP in a hepatoma cell line, which are significantly positively correlated." (PMID 31973032, 2020). "α-fetoprotein (AFP)-L3 represents a new generation of tumor marker for hepatocellular carcinoma (HCC)." (PMID 32549277, 2020). "A few previous studies reported normal AFP in TB patients, but increased AFP in TB patients with hepatocellular carcinoma." (PMID 32493477, 2020). "The most prominent of these include glypican 3 (GPC3), alpha-fetoprotein (AFP), NY-ESO-1, SSX-2, human telomerase reverse transcriptase (hTERT), hepatocellular carcinoma-associated antigen-587 (HCA587), and melanoma antigen gene-A (MAGE-A)." (PMID 32784389, 2020). "Hepatoid adenocarcinoma is a very rare extrahepatic tumor characterized by a hepatocellular carcinoma-like histology and often produces AFP." (PMID 32093729, 2020). "Conventional markers, such as prostate-specific antigen (PSA), carbohydrate antigen 199 (CA199), and alpha-fetoprotein (AFP) are useful for screening prostate carcinoma, pancreatic carcinoma, and hepatic carcinoma, respectively." (PMID 33597967, 2020). "These two cells have different metastatic potential, and the AFP (alpha fetoprotein) expression is positive, consistent with the characteristics of hepatocellular carcinoma." (PMID 32433581, 2020). "For example, alpha-fetoprotein (AFP) is widely used for the diagnosis of hepatocellular carcinoma (liver cancer)." (PMID 31897235, 2020). "Previous studies have reported that 70%‐80% of patients with primary hepatocellular carcinoma have elevated serum AFP levels." (PMID 33090723, 2020). "CDR1as can sponge miR-1270 and upregulate the expression of AFP to promote tumor growth, invasion and metastasis in hepatocellular carcinoma." (PMID 33335899, 2020). "A value higher than 300 RLUs indicated an AFP concentration greater than 25 ng/mL, suggestive of the possible occurrence of hepatocellular carcinoma and the need for further clinical examination." (PMID 32752243, 2020). "Another study focused on bone metastases of hepatocellular carcinoma reported a series of prognostic factors, including Child-Pugh class A group, alpha-fetoprotein level more than 30 ng/mL, and higher T stage (>5 cm)." (PMID 32889800, 2020). "Blood/serum alpha-fetoprotein decreased rapidly on nitisinone in all but one patient, who later developed intrahepatic hepatocellular carcinoma." (PMID 33046095, 2020). "Alpha-fetoprotein (AFP) is a widely used biomarker for hepatocellular carcinoma (HCC) early detection." (PMID 32616055, 2020). "In the validation dataset of surgery‐eligible patients, we compared cfDNA CNV results to AFP expression levels, which are used for hepatocellular carcinoma diagnosis." (PMID 32458568, 2020). "Alpha fetoprotein is a glycoprotein that can be utilized for the early-stage diagnosis of hepatocellular carcinoma (HCC)." (PMID 33302537, 2020).
hepatocellular carcinoma (continued). "α-Fetoprotein (AFP) is a well-known cancer biomarker for hepatocellular carcinoma (HCC) and is used worldwide." (PMID 31451706, 2019). "Presence of liver cancer, i.e., cholangiocarcinoma and/or hepatocellular carcinoma, was confirmed using the AFP antibody staining." (PMID 30939854, 2019). "Comparison of the net benefits in clinical decisions regarding the diagnosis of hepatocellular carcinoma in cirrhotic patients with AFP < 400 μg/L." (PMID 32038998, 2019). "In this study, we systematically evaluated the role of combining serum levels of CA19-9 and CEA to AFP in diagnosing hepatocellular carcinoma." (PMID 31205886, 2019). "The use of alpha‐fetoprotein (AFP) testing for the surveillance, diagnosis, and prognosis of hepatocellular carcinoma (HCC) remains controversial." (PMID 31517445, 2019). "For what concerns the diagnostic prediction of hepatocellular carcinoma, our data indicate the superiority of SCCA-IgM over the “classic” serological biomarker, namely Alpha-fetoprotein." (PMID 31882893, 2019). "Alpha-fetoprotein (AFP) is expressed during fetal development; however, after birth, its expression is negligible except in the case of certain malignancies including hepatocellular carcinomas and teratomas, where AFP is expressed at high levels." (PMID 31681205, 2019). "The cut-off range, > 9 ng/ml (≥9.1 ng/ml), for AFP was set according to the hospital’s serum positivity for the AFP, which was also the indicative value for hepatocellular carcinoma in some hospitals." (PMID 30849953, 2019). "As the alpha-fetoprotein biomarker offers limited sensitivity and specificity for the early detection of hepatocellular carcinoma, the combination with des-gamma-carboxy prothrombin is necessary." (PMID 31284393, 2019). "For hepatocellular carcinoma, several serum biomarkers (i.e. Alpha-fetoprotein and its L3 isoform, Protein Induced by Vitamin K Absence-II, Osteopontin...) are currently available in clinical practice, even if their use is not validated nor regulated." (PMID 31882893, 2019). "The clinical utility of serum alpha-fetoprotein (AFP) in patients with hepatocellular carcinoma (HCC) is widely recognised." (PMID 31285588, 2019). "In our previous work, we found that AFP combined with serum fluorescence intensity and conventional laboratory tests was valuable in the diagnosis of primary hepatic carcinoma." (PMID 32038998, 2019). "Alpha-fetoprotein (AFP) is a useful tumor marker for primary hepatocellular carcinoma and yolk sac tumor." (PMID 29457212, 2019). "Serum AFP is currently the most commonly used as diagnosis and surveillance for hepatocellular carcinoma." (PMID 31164099, 2019). "In another study, the circRNA hsa_circ_0004018 was down-regulated in hepatocellular carcinoma compared to para-tumorous tissue and correlated with decreased serum alpha-fetoprotein level, as well as tumor diameter, differentiation and stage." (PMID 31636510, 2019). "The tumor cells were positive for AFP, a useful marker for early tumor detection of hepatocellular carcinoma." (PMID 29351804, 2018). "AFP plays an important role in the development of hepatocellular carcinoma, which can serve as a target for immunotherapy of HCC." (PMID 29805966, 2018). "Alpha-fetoprotein (AFP) is an oncofetal antigen expressed during fetal development and by over 50% of hepatocellular carcinomas (HCC)." (PMID 30400822, 2018). "In 2015, an Egyptian research confirmatively demonstrated that the sensitivity of MK was significantly higher than that of alpha-fetoprotein in diagnosing hepatocellular carcinoma." (PMID 30200153, 2018). "In some tumors, such as hepatocellular carcinoma and yolk sac tumors, AFP is produced, which leads to an increase in serum AFP level." (PMID 30191347, 2018). "Significant elevations in alpha-fetoprotein should raise suspicion for hepatocellular carcinoma as malignancies with metastasis to the liver can elevate the alpha-fetoprotein level but typically <300 ng/mL." (PMID 30847183, 2018).